RING1 (ring finger protein 1)
Diseases named in the same sentence as RING1 in open-access papers (continued):
Sharing a sentence is not in itself a finding about the gene and the disease.
prostate carcinoma (1 paper, 2020). A carcinoma that arises from epithelial cells of the prostate gland. "RING1 was significantly overexpressed in high GS (Gleason score) prostate cancer, extraprostatic extension, and positive surgical margins, and can be used as a valuable predictive marker for PSA recurrence after radical prostatectomy." (PMID 33634028, 2020).
cancer (17 papers, 2009 to 2025). A tumor composed of atypical neoplastic, often pleomorphic cells that invade other tissues. "In this study, the dysregulation of RING1 was observed in multiple types of cancers and was associated with poor outcomes." (PMID 33634028, 2020). "Since promoter hypermethylation is an important cause for a low expression of a tumor suppressor gene in cancer, we hypothesized that the low expression of RING1 is regulated by its promoter hypermethylation." (PMID 33634028, 2020). "Dysregulation of RING1 expression or activity is involved in the development and progression of various diseases, including cancer, neurological disorders, and immune disorders." (PMID 41362702, 2025). "For instance, in hepatocellular carcinoma, RING1 promotes cancer stem cell self‐renewal and metastasis through the Wnt/β‐catenin pathway activation." (PMID 41362702, 2025). "In cancer, RING1 plays a critical role in regulating oncogenic signaling pathways, such as the Wnt/β‐catenin and Notch, and promotes cancer cell survival and growth." (PMID 41362702, 2025). "The catalytic components of PRC1 such as RING1 A or B/BMI1 complex are associated with several cancers and correlate with poor prognosis, thus PRC1 represents an attractive therapeutic target for cancer." (PMID 36881608, 2023). "When combining these results with the result of the expression profiling analysis, we found that RING1 low expression is an unfavorable cancer prognostic factor." (PMID 33634028, 2020). "For cancer, recent studies have shown that the abnormal gene expression of RING1 leads to the development of a variety of cancers." (PMID 33634028, 2020). "This study indicated that RING1 overexpression predicts better prognosis in some type of cancers." (PMID 33634028, 2020). "We further conducted survival analyses using the website of Kaplan–Meier Plotter to determine whether RING1 has a favorable or unfavorable prognostic role in different types of cancers in patients." (PMID 33634028, 2020). "Moreover, RNA-Seq data of 9,130 pan-cancer samples from TCGA datasets was analyzed using the XENA website tools to explore the correlation between the RING1 mRNA expression level and survival status in patients." (PMID 33634028, 2020). "RING1 transcriptional level in various human cancers was analyzed using TCGA database." (PMID 33634028, 2020). "Moreover, RING1 overexpression induces the transformation of hepatic progenitor cells into cancer stem cells through the activation of the Wnt/β-catenin signaling pathway." (PMID 33634028, 2020). "RING1 expression level in multiple cancer types was evaluated using the XENA and UALCAN databases." (PMID 33634028, 2020). "In this study, we first found that RING1 was abnormally expressed in different type of cancers." (PMID 33634028, 2020). "The interaction of RING1 and the oncogenic proteins such as MLL-AF9 and MLL-ENL in the leukemic cells may contribute to the growth of cancer cells and increase the risk of relapse post-HSCT31,32." (PMID 31551439, 2019). "However, in GCN and GC samples from 20 cancer patients, such correlation was progressively disturbed, especially between Cbx7 and Ring1/Mel18." (PMID 21060834, 2010). "However, only a limited number of studies on the role of RING1 in cancer, is available." (PMID 33634028, 2020). "To initially assess whether PRC1 components are altered in cancer, we examined the mutational frequencies of the histone H2A mono-ubiquitin ligases RNF2 (encoding RING1B) and RING1, the cPRC1 genes, and the core PRC1-encoding genes in large-scale genomic data sets from cancer patients." (PMID 30139998, 2018).
cancer (continued). "Interestingly, in Normal tissues from 18 non-cancer patients, we found that transcription of Cbx7 was positively correlated with those of Ring1, Bmi1, Mel18, and Phc2, but not with those of Cbx8 and Ezh2 (Ps<0.01)." (PMID 21060834, 2010).
tumor (7 papers, 2009 to 2025). "Along with the in vitro results, stable RING1 KD significantly promoted the tumor growth in xenograft model and also tumor volume and tumor weight were increased than shControl groups." (PMID 41362702, 2025). "In the quadriceps, muscle RING-finger protein-1 (MURF1) mRNA content was significantly increased at 4 weeks of tumor bearing compared with PBS controls." (PMID 36346680, 2022). "Next, we analyzed the correlation between RING1 protein expression and a series of clinicopathological features, including patient and tumor characteristics." (PMID 33634028, 2020). "Compared with solid normal tissue groups, RING1 mRNA expression level was significantly upregulated in the primary tumor groups." (PMID 33634028, 2020). "As a binding protein of RING1 and YY1, RYBP can exert a tumor suppressor effect and a good prognostic factor may depend on the role of RING1." (PMID 33634028, 2020). "In addition, were also measured the expressions of miR-637 and RING1 in the subcutaneous tumours of both groups." (PMID 30518760, 2018). "RING1 is over-expressed in various tumours and plays a role as an oncogene in tumours." (PMID 30518760, 2018). "Moreover, the immunohistochemistry assay showed that the tumours from the C5orf66-AS1-siRNA group exhibited reduced Ki-67 and RING1 staining compared with the control group." (PMID 30518760, 2018). "In addition, western blot was performed on tumor mass extracted from a xenograft model using A549 cells expressing shRING1, and similar to the results at the cell level, a tendency for CIP2A and c‐MYC to increase due to RING1 KD was confirmed." (PMID 41362702, 2025).
infection (1 paper, 2010). The state of being infected such as from the introduction of a foreign agent such as serum, vaccine, antigenic substance or organism. "For example, an E3 ubiquitin ligase, RING1, is induced by pathogen infection, localizes to plasma membrane lipid rafts, and can trigger programmed cell death in A. thaliana." (PMID 21192820, 2010).
neurodevelopmental disorder (1 paper, 2024). A behavioral and cognitive disorder with onset during the developmental period that involves impaired or aberrant development of intellectual, motor, or social functions. "RING1 mutations are likely a cause of human neurodevelopmental disorders where epigenetic effects play an important role." (PMID 38486307, 2024).
RING1 also shares sentences with these, for which no sentence is quoted: acute myelogenous leukemia (2 papers); colorectal cancer (2); glioma (2); pancreatic cancer (2); breast invasive carcinoma (1); colitis (1); dysplasia (1); esophageal cancer (1); glioblastoma (1); graft versus host disease (1); immune dysfunction (1); invasive ductal carcinoma (1); invasive lobular carcinoma (1); Kidney Chromophobe (1); lung adenocarcinoma (1); myelodysplastic syndrome (1); neurodegenerative disease (1); non-small cell lung carcinoma (1); osteosarcoma (1); ovarian carcinoma (1); pancreatic ductal adenocarcinoma (1); paraganglioma (1); Parkinson disease (1); pheochromocytoma (1); psychosis (1); schizophrenia (1); status epilepticus (1); synovial sarcoma (1); T cell deficiency (1); thymoma (1).
A further 3 diseases each share a sentence with RING1 in 1 paper.